SPATA31A7 (SPATA31 subfamily A member 7)
Description:
May play a role in spermatogenesis.
Synonyms: FAM75A4; FAM75A7; SPATA31A4; AEP1; C9orf36; C9orf36A
Tractability: Antibody: UniProt predicts a signal peptide or a membrane-spanning region.
Gene: Protein-coding gene on chromosome 9 (61,190,036 to 61,196,280, forward strand). Ensembl gene ENSG00000276040.
Subcellular location: Membrane
Subcellular location (Human Protein Atlas): Acrosome; Equatorial segment
Gene Ontology:
Molecular function: protein binding
Cellular component: membrane
Genetic constraint (gnomAD): Loss-of-function variants: 2 observed, 10.94 expected, observed/expected ratio (o/e) 0.18, 90% interval 0.074 to 0.58. The synonymous counts are far from expectation, so gnomAD's model fits this gene poorly and the ratio says little. Missense variants: 20 observed, 151.79 expected, observed/expected ratio (o/e) 0.13, 90% interval 0.092 to 0.19. Synonymous variants: 8 observed, 59.9 expected, observed/expected ratio (o/e) 0.13, 90% interval 0.077 to 0.24.
Homologues: Orthologues: mouse Spata31 (27% identical), rat Spata31 (27% identical). Paralogues in human: SPATA31A5 (99% identical), SPATA31A3 (99% identical), SPATA31A1 (98% identical), SPATA31A6 (98% identical), SPATA31C1 (76% identical), SPATA31C2 (73% identical), SPATA31E1 (33% identical), SPATA31D1 (27% identical), SPATA31D3 (18% identical), SPATA31D4 (18% identical), SPATA31F1 (18% identical), SPATA31F3 (2% identical).
Diseases named in the same sentence as SPATA31A7 in open-access papers:
SPATA31A7 is named in the same sentence as 2 diseases in open-access papers, as found by Europe PMC text mining. Sharing a sentence is not in itself a finding about the gene and the disease.
SPATA31A7 shares sentences with these, for which no sentence is quoted: bacterial infection (2 papers); glioma (1).